CTLA4 (cytotoxic T-lymphocyte associated protein 4)
Diseases named in the same sentence as CTLA4 in open-access papers (continued):
Sharing a sentence is not in itself a finding about the gene and the disease.
melanoma (continued). "It has been shown that antibody treatment in a murine model of melanoma reduces the number of CTLA-4+ T regulatory cells within the TME in an FcγR-dependent manner." (PMID 38567059, 2023). "Since both genes are co-located on chromosome 2 q33.2, are members of the CD28 immune checkpoint receptor family, are co-expressed in melanomas from the TCGA cohort, we expected co-expression of ICOS and CTLA4 in melanoma cell lines as well." (PMID 37259155, 2023). "Non-classical monocytes are crucial for ICI therapy of patients with malignant melanoma, since they are involved in the killing of regulatory T cells via the CTLA-4 mAb." (PMID 37835567, 2023). "We first confirmed that levels of CTLA4 were downregulated in whole blood samples from melanoma patients compared to healthy donors." (PMID 37197667, 2023). "Given that anti-CTLA-4 agents are used to treat melanoma patients, it is expected that these reactions will mainly affect melanoma cases that are routinely exposed to these agents in combination with PD-1 blocking agents." (PMID 37046745, 2023). "In 2011, the U.S. Food and Drug Administration approved ipilimumab, an anti-CTLA-4 antibody, for melanoma to increase the mobility of T cells and allow the cytotoxic T cells to continue to destroy cancer cells." (PMID 36766849, 2023). "We have previously shown that CpG methylation (CpG site covered by Infinium BeadChip bead cg08460026) of the co-localized CTLA4 gene predicts response to ICB in melanoma and clear cell renal cell carcinoma." (PMID 37259155, 2023). "EZH2 inactivation reversed the resistance to anti-CTLA-4 and IL-2 immunotherapy and suppressed melanoma growth in mice models." (PMID 37427115, 2023). "The survival of mice with melanoma increased after receiving the anti-CTLA-4 nanobody (Nb16) treatment because of the significant tumor growth inhibition." (PMID 36761751, 2023). "The combination of CTLA-4 and PD-1 blockade has been shown to improve survival in patients with melanoma, renal cell carcinoma, and many other cancers." (PMID 36761748, 2023). "This included Bacteroides Fragilies and anti-CTLA-4 therapy in melanoma mice, resulting in better immune response." (PMID 37111629, 2023). "For example, in melanoma, the response rate of patients with CTLA-4 or PD-1 blockade is only 20%-40%." (PMID 37189103, 2023). "In short, BST2 is part of an anti-CTLA4 response in melanoma and CLIC2 is a favorable prognosis biomarker." (PMID 38269333, 2023). "Immune checkpoint inhibitor (ICI)-based therapies, specifically anti-cytotoxic T lymphocyte-associated antigen-4 (anti-CTLA-4) and anti-programmed death-1 (anti-PD-1) antibodies, have transformed our understanding and management of melanoma in recent years." (PMID 37903733, 2023). "For instance, data from CheckMate 067 support the use of anti-PD-1 plus anti-CTLA-4 over anti-PD-1 alone or anti-PD-1 plus anti-LAG-3 in patients with BRAF mutant melanoma." (PMID 37507765, 2023). "Cox PH analysis was also applied to compare the cumulative death rates in two log-CTLA4 level subgroups based on the cut-point in the respective US melanoma cohort." (PMID 37197667, 2023). "Given that CTLA-4 blockade can lead to tumor regression in murine models, multiple studies concluded with the clinical development and approval of anti-CTLA-4 monoclonal antibodies (mAb) for the treatment of patients with advanced melanoma." (PMID 38162657, 2023). "We investigated the mechanisms of CTLA4 downregulation by melanoma cell secretome in human Treg cells." (PMID 37197667, 2023). "Another humanized anti-CTLA-4 antibody, tremelimumab, obtained durable responses in phase I/II clinical studies in melanoma, but failed in a phase III randomized clinical trial." (PMID 37371615, 2023). "Ipilimumab was the first inhibitor of CTLA-4 which enhanced viability and responses against tumors in patients with developed melanoma." (PMID 37605149, 2023).
melanoma (continued). "The FDA-registered immune-based therapeutics for resected stage III/IV melanoma include anti–PD-1, anti-CTLA-4, and interferon-based therapies." (PMID 36980641, 2023). "The combination of Programmed Cell Death 1 (PD-1) and Cytotoxic T-Lymphocyte Antigen 4 (CTLA-4) blockade has dramatically improved the overall survival rate for malignant melanoma." (PMID 36934257, 2023). "In Asian patients with advanced BRAF V600‐mutant melanoma, the superiority of first‐line PD‐1/CTLA‐4 over BRAF/MEKi appears modest." (PMID 37584204, 2023). "Similar results were also reported in another study using mice with melanoma treated with anti-CTLA-4 antibodies." (PMID 37298653, 2023). "Our previous study reported the immune profiles of melanoma patients treated with anti-PD-1 monotherapy or combined anti-CTLA-4 dual therapy based on WTS data." (PMID 37055772, 2023). "TMB-high melanoma is associated with a higher overall response rate to ICI with anti- PD-1 and/or anti-CTLA-4 antibodies and improved overall survival." (PMID 35192052, 2023). "To date, three immune checkpoint inhibitors have been approved for the treatment of melanoma: the anti-PD-1 antibodies nivolumab and pembrolizumab and the anti-CTLA-4 antibody ipilimumab." (PMID 37221594, 2023). "In patients with melanoma, CTLA-4 inhibitor-induced irAEs were reported to be negatively associated with a high proportion of the Bacteroidetes phylum but positively associated with the Faecalibacterium genus and other Firmicutes species." (PMID 37055838, 2023). "Recent evidence has indicated that methylation levels of CTLA4 promoter predict therapeutic response in patients affected by melanoma and clear renal cell carcinoma." (PMID 37601778, 2023). "In this study, we analyzed the expression of CTLA4 mRNA in tumor and blood samples from melanoma patients and found a correlation between decreased tumor and blood CTLA4 and a poorer prognosis in patients with metastatic melanoma." (PMID 37197667, 2023). "These drugs have 40–60% response rates when used as monotherapies, with many of those responses lasting a long time.b)CTLA-4 Inhibitors: Ipilimumab is a CTLA-4 inhibitor used in advanced melanoma treatment." (PMID 37803407, 2023). "The advent of immune checkpoint inhibitors (ICIs), such as anti-programmed cell death protein 1 (PD-1) and anti-cytotoxic T-lymphocyte associated protein 4 (CTLA-4) antibodies (Abs), has revolutionized the treatment of patients with advanced melanoma." (PMID 37046775, 2023). "Here, we used a preclinical melanoma model and anti-PD-1/CTLA-4 therapy to show that ICT induces translocation of specific gut bacteria into secondary lymphoid organs and tumors, which activates dendritic cells (DC) and primes anti-tumor T cell responses." (PMID 36867675, 2023). "Melanoma cells can express some inhibitory molecules, such as Programmed cell death 1 ligand 1 (PD-L1) and Cytotoxic T-lymphocyte protein 4 (CTLA-4), to block T-cell activation and function activities." (PMID 37174106, 2023). "Since BRAF V600‐mutant melanoma responded better to PD‐1/CTLA‐4 in the CheckMate 067 trial, Anti‐PD‐1 and PD‐1/CTLA‐4 should be evaluated separately." (PMID 37584204, 2023). "Gut microbiome is also associated with toxicity, as supported by an analysis involving 77 patients with advanced melanoma treated with anti-CTLA-4 in combination with anti-PD-1 therapy." (PMID 37520576, 2023). "The anti-CTLA-4 antibody ipilimumab was the first immune checkpoint antibody approved for the treatment of patients with advanced melanoma." (PMID 37046650, 2023). "Long-term overall survival can be achieved in 54% of advanced melanoma patients with combined anti-CTLA-4 and anti-PD-1 blockade although durable response is less common in mucosal and ocular melanoma." (PMID 37371056, 2023). "When combined with anti-CTLA-4, G47Δ, a triple-mutated oncolytic HSV-1, increased the influx of effector T cells into the TME in various cancer mouse models, including melanoma." (PMID 38139110, 2023).
melanoma (continued). "Zheng et al112 examined the CSC‐directing impact of the CSC‐DC vaccine which was combined with a dual suppression of PD‐L1 and CTLA‐4 in an in vivo model for the melanoma tumor." (PMID 37698048, 2023). "This study aimed to assess the efficacy of first‐line BRAF/MEKi, Anti‐PD‐1, and PD‐1/CTLA‐4 in Asian patients with advanced BRAF V600‐mutant melanoma in a real‐world setting." (PMID 37584204, 2023). "For example, combining anti-PD-1/PD-L1 agents with anti-CTLA-4 agents has shown improved response rates in patients with melanoma and renal-cell carcinoma." (PMID 37111629, 2023). "In melanoma patients treated with an anti-CTLA-4 antibody, peripheral eosinophils were observed at the time of skin eruption." (PMID 37046745, 2023). "It has been shown that inhibiting EZH2 reversed acquired resistance and enhanced anti-tumor effects when in combination with anti-PD1, anti-CTLA-4, and IL-2 immunotherapy in prostate cancer and melanoma." (PMID 37386520, 2023). "The first of these models is illustrated by a study where a CTLA-4 antibody was used to deplete TREG specifically within the TME in a model of melanoma." (PMID 37139854, 2023). "Tremelimumab is another anti-CTLA-4 antibody effective for melanoma, gastric cancer, esophageal cancer, and non-small cell lung cancer." (PMID 36604694, 2023). "In the Nathanson dataset, melanoma patients with low TIIC signature scores showed better survival outcomes, and melanoma patients with low TIIC signature scores presented better responses to anti‐CTLA‐4 immunotherapy." (PMID 36822595, 2023). "Following the first success of melanoma treatment, immune checkpoint inhibitors, including anti-PD-L1 and anti-CTLA-4, now play a more critical role in immunotherapy." (PMID 37421455, 2023). "To test the involvement of miRNAs in melanoma secretome-mediated CTLA4 mRNA instability, we cultured human Treg cells in the absence or presence of 50% 1205Lu-MCM for 24 h and analyzed mature miRNA expression by RT-PCR." (PMID 37197667, 2023). "CTLA-4 inhibitors, such as ipilimumab, have been approved for the treatment of melanoma, and combinations of PD-1 and CTLA-4 inhibitors are being investigated for the treatment of several types of cancer." (PMID 37345057, 2023). "In the scope of immunotherapy, few studies assessed 18F-FDG PET/CT as an early predictor of responses to PD-1 or CTLA-4 blockades in patients with non-small-cell lung carcinoma or melanoma." (PMID 36768822, 2023). "The 5-year survival rates for melanoma reached an unprecedented 52% when applying the combined CTLA-4 and PD-1 blockade approach." (PMID 37454231, 2023). "A small retrospective analysis of testicular biopsies of patients treated with anti-PD1 and anti-CTLA4 showed impaired spermatogenesis in six out of seven (85%) patients with melanoma." (PMID 37240854, 2023). "Here, we present preclinical evidence for combining domatinostat with anti-PD-1 ± anti-CTLA-4 in a melanoma tumor model, and report the first results of the DONIMI trial (NCT04133948)." (PMID 36920329, 2023). "Ipilimumab was the first ICI authorized by the FDA in 2011; it serves as an antibody against CTLA-4 that can be used to treat advanced melanoma via suppression of the inhibitory signal of CTLA-4 to induce activated CTL." (PMID 37194085, 2023). "Similar to whole blood samples, CTLA4 levels were downregulated in CD45+ cells from melanoma patients compared to healthy donors." (PMID 37197667, 2023). "Our study is the first to evaluate pretreatment NER as a prognostic biomarker in advanced melanoma patients receiving anti-PD-1 monotherapy or combined anti-CTLA-4/PD-1." (PMID 37903733, 2023). "Roesch and colleagues use clinical datasets and mouse models of BRAF-mutant melanoma to reveal a role for IL-17A in positive responses to anti-PD-1 and anti-CTLA-4 therapy, which they also link to infiltrating neutrophils." (PMID 37525015, 2023).
melanoma (continued). "The PD-1/PD-L1 axis is a main mediator of CD8+ T cell exhaustion with in the TIME of resistant melanomas after combined treatment with RT and an anti-CTLA-4 ICI." (PMID 37377970, 2023). "We utilized the B16/F10 melanoma model and performed serial in vivo and in vitro passaging in the presence of an anti-PD-L1 and anti-CTLA-4 antibody." (PMID 36650153, 2023). "The application of immune checkpoint inhibitors (ICI), including antibodies against programmed cell death protein 1 (PD-1) and cytotoxic T-lymphocyte protein 4 (CTLA-4) significantly increased survival and response rates for advanced melanoma patients." (PMID 36860876, 2023). "In particular, only 20% melanoma patients respond to anti-CTLA-4 treatment, 30-40% respond to anti–PD-1 antibodies and 58% show clinical response to the combination therapy with these antibodies." (PMID 36860876, 2023). "Patients with a low H4Mscore had a significant survival advantage in another melanoma cohort treated with anti-PD-1 and anti-CTLA4 inhibitors (GSE91061)." (PMID 36932439, 2023). "B78 melanoma bearing mice treated with RT + IC + anti-CTLA-4 generated an antibody response to surface proteins on the B78 (or B16) tumor cells that was measurable at day 22 post tumor implantation." (PMID 38077403, 2023). "The anti-CTLA-4 antibody ipilimumab (Yervoy) was the first approved ICI recommended for the therapy of melanoma in 2011, followed a few years later by the anti-PD-1 nivolumab for non-small-cell lung cancer (NSCLC)." (PMID 36831435, 2023). "The combination of PS-targeting mAbs with immune checkpoint blockade (anti-cytotoxic T-lymphocyte associated protein 4 (CTLA-4) or anti-PD-1) was evaluated in breast and melanoma syngeneic models of cancer in immunocompetent mice." (PMID 37446286, 2023). "In 2011, the Food and Drug Administration (FDA) approved the use of ipilimumab, a fully human, IgG1κ monoclonal, anti-CTLA-4 antibody in advanced melanoma." (PMID 36978794, 2023). "Anti-CTLA4 is widely used in the treatment of melanoma because it blocks the inhibitory signal involving CTLA4 molecules between antigen-presenting cells and T lymphocytes." (PMID 37266661, 2023). "In other cancer types, notably melanoma and non-small-cell lung cancer, immunotherapeutic approaches, including immune checkpoint inhibitors (such as anti-PD-1 and anti-CTLA-4 antibodies), have demonstrated remarkable success in improving patient outcomes." (PMID 38066539, 2023). "For melanomas, only 17%–26% of patients respond to anti-PD-L1 therapy and only 2%–6% respond to anti-CTLA-4 therapy." (PMID 37427373, 2023). "The severity of patients diagnosed with melanoma, lung, renal, and bladder cancers significantly improved and benefited from anti-CTLA-4 and anti-PD-1 monotherapies." (PMID 36813833, 2023). "Icaritin plus anti-PD-1/CTLA-4 treatment reduced the growth of melanoma cell line in C57BL/6 mice by 65% compared to anti-PD-1/CTLA-4 treatment alone (34.2%)." (PMID 37622107, 2023). "The predominant immunotherapy treatments employed for melanoma include anti-CTLA-4 and anti-PD-1 antibodies, which function by targeting and inhibiting specific receptors found on T cells." (PMID 38077400, 2023). "In patients with melanoma treated with a CTLA4 blocking antibody, IRAK3 mRNA in the blood is included in a 4-gene panel to predict patient outcome." (PMID 36757800, 2023). "In melanoma, lower m6Ascores always correlated with more sensitive anti-PD-1 and anti-CTLA4 treatment responses." (PMID 37598390, 2023). "In intracranial disease, early trials investigating single-agent immune checkpoint inhibition (ICI) with ipilimumab (anti-CTLA-4) in melanoma BrM showed some efficacy with 18–24% intracranial response rate." (PMID 38567052, 2023). "The most common primary cancer was melanoma and most patients with taking both CTLA-4 and PD-1 inhibitors." (PMID 37250639, 2023).
melanoma (continued). "The results revealed the importance of time-dependent changes in tyrosine nitration in the PBMCs obtained from patients with melanoma who were undergoing anti-CTLA-4 therapy and experienced long RFS rates." (PMID 36980641, 2023). "Expression of CTLA-4 on tumor cells represents a dismal prognosis in melanoma and in pancreatic, nasopharyngeal, and breast cancers." (PMID 37189748, 2023). "In this multi‐center real‐world data study, we analyzed the clinical efficacy of first‐line BRAF/MEKi, Anti‐PD‐1, and PD‐1/CTLA‐4 therapies in 336 Asian patients with advanced BRAF V600‐mutant melanoma." (PMID 37584204, 2023). "Melanoma has been at the forefront of immunotherapy with at least three checkpoint targets to date, namely PD-1, CTLA-4, and LAG-3, being first FDA approved in metastatic disease." (PMID 37484526, 2023). "The aim of our review is to enrich the understanding of the dynamic interplay between melanoma, immune checkpoints and immune cells, and to provide an update on currently investigated ICIs, beyond anti-PD-1 and anti-CTLA-4 agents." (PMID 37345056, 2023). "Combination therapy with radiation and anti-PD-1/PD-L1 or anti-CTLA-4 has significantly improved efficacy in patients with lung cancer and melanoma." (PMID 37833255, 2023). "Melanoma patients with low TIIC signature scores presented better responses to anti‐CTLA‐4 immunotherapy." (PMID 36822595, 2023). "In 2010, the CTLA-4 antibody ipilimumab was approved for the treatment of melanoma following a successful phase III trial." (PMID 38201559, 2023). "Pseudoprogression has been frequently reported in patients with melanoma receiving anti-CTLA-4 treatment, whereas it is rare in other tumor types and with anti-PD1/PD-L1 treatment." (PMID 36575286, 2023). "Similar to the AUS cohort survival analysis, US cohort melanoma patients (n = 263) were segregated as CTLA4 high and low expressers based on the optimized cut point (log –4.21) for survival analysis." (PMID 37197667, 2023). "On the other side, one study on melanoma patients receiving anti-CTLA-4 treatment showed that the enrichment of Bacteroidetes is strongly correlated with less frequency of colitis, which was supported by others." (PMID 36969071, 2023). "CTLA-4 is expressed at low levels in peripheral blood, but this is significantly upregulated in ILC1s infiltrating human malignant breast tumors, and melanoma, while, it is expressed at much lower levels in hepatocellular carcinoma." (PMID 38567059, 2023). "Among them, the PD-L1 (CD274) gene expression level is a validated biomarker for anti-PD-1 monotherapy and anti-PD-1 + anti-CTLA-4 in advanced melanoma." (PMID 37055772, 2023). "Lower diversity indices were observed in advanced disease stages and upon anti-CTLA-4 therapy in melanoma patients." (PMID 37928542, 2023). "Combined sympathetic and CTLA-4 blockade inhibits murine melanoma growth by targeting infiltrating T cells." (PMID 37347365, 2023). "In this context, two immunological checkpoints become the main therapeutic targets for melanoma: cytotoxic T-lymphocyte antigen 4 (CTLA-4) and programmed cell death protein-1 (PD-1)." (PMID 36768978, 2023). "For instance, melanoma treated with an ICB combination of anti–PD-1 and anti-cytotoxic T lymphocyte–associated protein 4 (anti–CTLA-4) antibodies displayed similar intracranial and extracranial response rates." (PMID 37655659, 2023). "The anti-Cytotoxic T-Lymphocyte Antigen 4 (CTLA-4) antibody Ipilimumab was the first ICI to demonstrate important efficacy results in patients with advanced melanoma." (PMID 38201531, 2023). "Currently, immune checkpoint inhibitors based on CTLA-4 and PD-1 have been approved for the immunotherapy of melanoma." (PMID 37305390, 2023). "Recent systematic literature reviews concluded that the superiority of combined anti-CTLA-4 and anti-PD-1 therapy for melanoma and NSCLC in the response rates or OS has been proven to date, which is contrary to our conclusion (p = 0.32 and p = 0.1)." (PMID 36765640, 2023).